ENSG00000285505 (novel protein, ATP1A3-RABAC1 readthrough)
Gene: Protein-coding gene on chromosome 19 (41,956,879 to 41,994,232, reverse strand). Ensembl gene ENSG00000285505.
Genetic constraint (gnomAD): Missense variants: 501 observed, 1,447 expected, observed/expected ratio (o/e) 0.35, 90% interval 0.32 to 0.37. Synonymous variants: 540 observed, 591.01 expected, observed/expected ratio (o/e) 0.91, 90% interval 0.85 to 0.98.